RN7SL474P (RNA, 7SL, cytoplasmic 474, pseudogene)
Gene: Miscellaneous RNA gene on chromosome 8 (16,863,196 to 16,863,496, reverse strand). Ensembl gene ENSG00000264092.
Homologues: Paralogues in human: Metazoa_SRP (81% identical), RN7SL811P (81% identical), RN7SL134P (80% identical), RN7SL774P (80% identical), RN7SL96P (80% identical), RN7SL154P (79% identical), RN7SL784P (78% identical), Metazoa_SRP (78% identical), RN7SL123P (78% identical), RN7SL391P (78% identical), RN7SL339P (76% identical), RN7SL693P (76% identical), and 710 more.